MERTK (MER proto-oncogene, tyrosine kinase)
Diseases named in the same sentence as MERTK in open-access papers (continued):
Sharing a sentence is not in itself a finding about the gene and the disease.
tumor (continued). "Preclinical studies with small molecular weight inhibitors of MerTK and Axl have been shown to alter the tumor immune landscape to favor anti-tumor immune activity, thus it is anticipated that antibody-mediated inhibition of TAM receptors will also alter the tumor immune landscape." (PMID 32087708, 2020). "In addition to engineered recombinant cell lines, the ability of INCB081776 to modulate AXL and MERTK activity was evaluated in tumor cell lines expressing high levels of endogenous AXL or MERTK." (PMID 33425754, 2020). "The recently uncovered function of MERTK on activated T cells could have an important impact on anti-tumor immunity." (PMID 31664482, 2020). "However, the combined inhibition of MERTK and indoleamine-2,3-dioxegenase (IDO1) blocked tumor metastasis and caused tumor regression in 60% of MMTV-Neu mice." (PMID 32346605, 2020). "However, another study showed that MerTK and AXL-deficient mice exhibit exacerbated tumor growth and inflammation associated cancer." (PMID 32802188, 2020). "TAM receptors, Axl and MerTK, are also expressed by tumor cells in many tumor types." (PMID 32087708, 2020). "Collectively, this leads us to believe that high TAM receptor-expressing cells (whether APCs or cancer cells) can compete with MERTK-expressing T cells for the PROS1 ligand in the tumor microenvironment or periphery." (PMID 31664482, 2020). "Furthermore, we present evidence of MerTK expression in tumor-infiltrating immune cells in multiple cancer indications." (PMID 33101282, 2020). "Moreover, MerTK-driven efferocytosis also induces the expression of the programmed death-ligand 1 (PD-L1), a molecule that promotes tumor escape, and therefore enhances the immune suppression microenvironment for cancer cells." (PMID 32370748, 2020). "In addition, a recent study showed that MerTK expression on CD8+ T cells improves tumor-infiltrating lymphocyte expansion." (PMID 32802188, 2020). "The presence of tumor-associated macrophages (TAM) is also associated with the expression of efferocytosis receptors like MerTK, and the uptake of apoptotic tumor cells may promote further anti-inflammatory, tumor promoting polarization of TAMs." (PMID 31798592, 2019). "Collectively, these findings indicate a strategy of combined treatment with MerTK and NF-κB inhibitors could be effective for reducing tumor cell proliferation, potentially by altering the composition of immune/inflammatory cells in the tumor microenvironment." (PMID 31903163, 2019). "Further studies suggested that systemic treatment using a combination of MerTK and NF-κB inhibition could be effective for decreasing tumor growth." (PMID 31903163, 2019). "Importantly, MerTK ablation confers tumor immunity, increased pro- inflammatory cytokines and tumor lymphocyte infiltration." (PMID 30400822, 2018). "MerTK is closely related to tumor cell migration and invasion." (PMID 29554921, 2018). "We hypothesize that pharmacological targeting of MerTK with monoclonal antibodies (mAbs) may lead to a similar pro-inflammatory response and recapitulate the anti-tumor effects observed in MerTK-/- mice." (PMID 30400822, 2018). "Moreover, genetic ablation or pharmacologic inhibition of MerTK in these models reduced M2-like macrophages, decreased wound-healing cytokine production, and blocked formation of postpartum tumor metastases." (PMID 30187085, 2018). "Although further quantitative analysis is needed, it seems that when high levels of MerTK are present before treatment starts, the tumor cells may take advantage of other mechanisms to survive BRAF or combined BRAF/MEK blockade." (PMID 29050198, 2017). "In addition, exploration of MERTK expression levels in tumours using immunohistochemistry on tissue microarrays (TMAs) showed that high MERTK expression is a biomarker for worse overall, disease‐free and recurrence‐free survival in CRC patients." (PMID 29101300, 2017).
tumor (continued). "Future studies are warranted to explore whether MerTK expression and/or activation status in tumor tissues would be correlated with the response of GC patients." (PMID 29285287, 2017). "Induction of polyploidy in response to MERTK inhibition is a novel finding and reveals a new mechanism by which therapeutic agents targeting MERTK may mediate anti-tumor activity in GBM cells." (PMID 27783662, 2016). "In addition, in a transgenic mouse model forced MERTK expression leads to the development of a predominantly T-cell leukemia/lymphoma where transgenic mice have significantly lower tumor-free survival as compared to wild-type C57Bl/6 mice." (PMID 27834816, 2016). "We found a significant positive correlation between MERTK protein and mRNA expression and clinico-pathological features such as advanced tumor stage and the occurrence of lymph node metastases suggesting that MERTK expression occurs more often in aggressive tumors." (PMID 27081701, 2016). "Additionally, in a transgenic model of mammary gland carcinoma, reconstitution of lethally irradiated mice with MERTK−/− marrow again reduced tumor growth, highlighting the importance of MERTK in the hematopoietic system for tumor development." (PMID 27834816, 2016). "As the TAM RTKs are known to negatively regulate inflammatory immune responses, high DN10764 dosing may have targeted both AXL and MERTK, resulting in hyperinflammation in vivo, ultimately contributing to the promotion of tumor progression and metastasis." (PMID 27829217, 2016). "Moreover, in the Bonn HNSCC cohort, MERTK expression increased with higher tumor stages (p = 0.008) and more advanced regional lymph node status (p = 0.041)." (PMID 27081701, 2016). "Additionally, in the TCGA HNSCC cohort higher tumor grading correlated with higher MERTK mRNA (p < 0.001) and for the Bonn HNSCC cohort the same trend was evident (p = 0.246, Jonckheere trend test p = 0.094)." (PMID 27081701, 2016). "Additionally, shRNA against MerTK was shown to decrease tumor cell invasion through actomyosin contractility." (PMID 24658326, 2014). "However, the striking abrogation of tumor growth observed in immune-competent mice suggests that overexpressing MerTK may modulate the tumor immune microenvironment (TIME) in TNBC." (PMID 40391157, 2025). "Consequently, determining whether MERTK expression can serve as a marker for tumor progression is a central focus of this investigation." (PMID 40433916, 2025). "Expanding the sample size and performing additional immunohistochemistry across various PTC stages confirmed that MERTK expression in tumor cells aligns with trends observed in single‐cell data, suggesting that MERTK protein could serve as a biomarker for early diagnosis of PTMC progression." (PMID 40433916, 2025). "Furthermore, we report that tumor-bound MerTK and PD-L1 are expressed independently." (PMID 40391157, 2025). "recently reported that tumor growth in the 4T1 model could be abrogated by promoting a hotter TIME when blocking Tyro3, Axl, MerTK, and Met with the small molecule inhibitor sitravatinib and that this blockade enhances the anti-tumor effect of CDK4/6 inhibition." (PMID 40391157, 2025). "Additionally, KTX-978 induced degradation of MERTK in CT-26 tumor (murine colon carcinoma) in vivo." (PMID 39062902, 2024). "Of course, MERTK function may be required in more than one cell type for anti-tumor immunity." (PMID 38791338, 2024). "Therefore, promoting MerTK cleavage by ADAM17 may present a new therapeutic avenue in the tumor microenvironment." (PMID 38779685, 2024). "Moreover, MERTK knockdown was driving tumor cells into the cell cycle G0/G1 phase." (PMID 38203403, 2023). "Although the lack of anti-tumor resistance in Mertk-/-V2 and Mertk-/-V3 mice already pointed to a MERTK-agnostic basis for tumor clearance, we hypothesized that some of the coincidental changes in BMDMs in these mice might compensate for the loss of MERTK by providing redundancy in phagocytosis." (PMID 35969037, 2022).
tumor (continued). "An elegant work using two immunocompetent syngeneic murine models of BCa (4T1 and E0771) has investigated how differential expression of AXL expression on tumor cells and MERTK on immune host cells could cooperate to promote immune evasion and immunosuppression." (PMID 35572601, 2022). "Furthermore, combination therapy or the addition of PD-L1-binding moieties to the bispecific antibodies generated herein could enhance tumour cell-killing and avoid the upregulation of PD-L1 by MerTK in a potentially immunosuppressed TME." (PMID 36555321, 2022). "Taken together, harnessing MerTK expression on tumour-infiltrating macrophages via bispecific antibodies binding to tumour-specific markers might pave the way for interesting therapeutic strategies resulting in the targeted phagocytosis of tumour cells." (PMID 36555321, 2022). "In addition, due to the important physiological role of MerTK in the innate immune system, MerTK inhibitors may potentially reduce tumor growth by changing the immunosuppressive environment and stimulating antitumor immunity." (PMID 35268561, 2022). "Indeed, this may be related to similar findings in in vivo studies where PD-1 blockade is required when using MERTK inhibitors, to achieve anti-tumor efficacy." (PMID 34835225, 2021). "Thus, MerTK blockade may represent a promising antitumor strategy that could significantly increase tumor immunogenicity and potentiate antitumor immunity." (PMID 33463063, 2021). "Thus, in at least some cases agents that target both AXL and MERTK may provide better tumor growth control than more selective compounds." (PMID 34830794, 2021). "Additionally, anti‐MerTK antibody treatment could stimulate T cell activation and synergize with anti‐PD‐1 or anti‐PD‐L1 therapies in tumor‐bearing mice." (PMID 33463063, 2021). "Despite the important roles of MERTK and FLT3 in immune cell development, little effort has been done to fully elucidate the effect that new generation of MERTK or FLT3 inhibitors may have on a prime component the anti-tumor immune response, namely cytotoxic CD8+ T cells." (PMID 34835225, 2021). "Thus, targeting MERTK in cancer may not only increase tumor immunogenicity but may also augment immune checkpoint inhibitor therapies through increasing tumor inflammation." (PMID 34065321, 2021). "MerTK and AxlTK receptors could play important roles in the development of MM: they act as direct drivers of the tumor progression and as inhibitory receptors in the cells of the tumor microenvironment that suppress host immunity." (PMID 32363092, 2020). "Therefore, targeting both AXL and MERTK kinases may directly impact tumor growth and relieve immunosuppression." (PMID 33425754, 2020). "However, strong MERTK expression was surprisingly detected in 8 of 21 tumours." (PMID 30765874, 2019). "Importantly, transplantation of MerTK−/− bone marrow into wild-type mice decreased tumor growth and altered cytokine production whereas transplantation of wild-type bone marrow had no such effects, strengthening the link to a leukocyte-specific role for the oncogenesis of MerTK." (PMID 30187085, 2018). "Thus, future studies should evaluate the phosphorylation status of MerTK in GC tumor tissues to investigate whether MerTK activation frequently occurs and whether it has prognostic or predictive value." (PMID 29285287, 2017). "Thus, co-targeting BRAFV600E and MerTK may substantially reduce tumour burden in mice, which pheno-copied the outcome of dual-inhibition of BRAFV600E and autophagy." (PMID 29050198, 2017). "In addition, it seems plausible that MERTK primarily shows indirect effects on prognosis by promoting tumor cell migration and thereby e.g. increases the number of lymph node metastases and the tumor stage, which in turn lead to worse survival." (PMID 27081701, 2016).
tumor (continued). "First, we describe important subpopulations of profibrotic and pro-tumor macrophages, including SPP1+, MERTK+, TREM2+, and MARCO+ cells, using high-resolution spatial and single-cell omics technologies." (PMID 41939908, 2026). "MerTK, a TAM receptor, regulates macrophage efferocytosisand polarization, and its inhibition holds potential for tumor growthsuppression and immune modulation." (PMID 40391976, 2025). "Targeted editing of key nodes—including MerTK, CD47, and SIRPα—enhances phagocytic capacity and potentiates antitumor immunity in preclinical tumor models." (PMID 41403915, 2025). "Recent studies have found that HSP70 secreted by tumor cells can bind to TLR2 on the surface of macrophages, forming an HSP70-TLR2 complex, which upregulates MerTK expression and promotes the polarization of macrophages to the M2 type." (PMID 40297581, 2025). "MerTK activation triggers multiple pro-oncogenic signaling pathways, including MAPK, p38, and PI3K, which consequently make tumor cells more aggressive in terms of survival, proliferation, and resistance to apoptosis." (PMID 41226428, 2025). "MerTK blockade inhibits apoptotic tumour cell clearance by macrophages, permitting cDC1s to induce an IFN‐I response and subsequent T cell‐dependent tumour control." (PMID 40878038, 2025). "Further supporting a role for Hsp70, TLR2, and MerTK, the tumors from Hsp70 KD LLC-GFP and LN229 cells, and LLC-GFP tumors from TLR2 null mice showed impaired MΦ polarization and tumor growth." (PMID 39941817, 2025). "In contrast, we report in this study that tumor-bound MerTK plays a unique role in promoting a hot TIME in TNBC, and high expression of tumor MerTK sensitizes tumors to ICI therapy." (PMID 40391157, 2025). "In progressive PTC (stages II and III), nearly all tumor cells exhibited strong MERTK expression, while AXL expression remained unchanged between normal and tumor tissues." (PMID 40433916, 2025). "In this study, we reveal that tumor-bound MerTK uniquely contributes to the development of a hot TIME in TNBC, with high MerTK expression on tumors enhancing their sensitivity to ICI therapy." (PMID 40391157, 2025). "First in the tumor cells, where AXL inhibition would disrupt developmental, proliferative, and migratory pathways, and second, in the tumor microenvironment, where MERTK suppression would modulate the innate immune response." (PMID 39924521, 2025). "Using tumor‐derived PGE2 from A375 CM, the addition of aEP2 or aEP2/4 downregulated CD163, MerTK, and CD14 expression, which indicates a less suppressive macrophage phenotype." (PMID 41211769, 2025). "Pharmacological inhibition of MerTK or AXL, when combined with radiotherapy or chemotherapy, augments the immunogenicity of tumor cell death, increases antigen release, and thereby strengthens adaptive immune activation." (PMID 41403915, 2025). "Our data suggested that overexpressing MerTK in TNBC cell lines led to increased proliferation and robust in vivo tumor growth." (PMID 38791148, 2024). "The addition of the MerTK ASO to the combination of radiotherapy and CPI in our study reliably induced an abscopal effect, with substantial reductions in secondary tumor growth and coordinated improvements in animal survival." (PMID 38443968, 2024). "Incorporating MerTK ASO with AZD6244 (selumetinib) and anti-PDL1 significantly enhanced tumor control." (PMID 38443968, 2024). "Given the increasing evidence that the TAM family can play an immunomodulatory role in the tumor immune microenvironment (TIME), we sought to explore the effects of dual Axl/MerTK inhibition on the TIME." (PMID 39457986, 2024). "In this study, we describe a link between MerTK, which is highly expressed in TNBC tumors, and cancer cell proliferation and tumor metastasis." (PMID 38791148, 2024). "Beyond immunoradiotherapy, we assessed the therapeutic efficacy of MerTK ASO in combination with chemotherapy, selumetinib, and either anti-PDL1 or anti-PD1 across different tumor models." (PMID 38443968, 2024).
tumor (continued). "Efferocytosis-related receptors, such as MerTK and AXL, have been found to play a role in promoting tumor progression." (PMID 38802814, 2024). "Our data suggest that MerTK regulates a unique proliferative signature in TNBC, promoting robust tumor growth and increased metastatic potential through ENG upregulation." (PMID 38791148, 2024). "The stable overexpression of MerTK in human TNBC cell lines induced an increase in proliferation rates, robust in vivo tumor growth, heightened migration/invasion potential, and enhanced lung metastases." (PMID 38791148, 2024). "The prevalence of CD4+CD45+ T cells was unaffected by MerTK inhibition in either tumor, as was the prevalence of CD8+CD45+ T cells in the primary tumor." (PMID 38443968, 2024). "In this study, we demonstrated that MerTK was an independent prognostic factor for GAC and that inhibition of MerTK not only reduced tumor progression but also enhanced the effect of 5‐FU‐based chemotherapy." (PMID 38545840, 2024). "In a model of MerTK overexpression, we identified the upregulation of endoglin (ENG), a small transmembrane receptor for TGFβ, as a key determinant of tumor metastasis in vivo." (PMID 38791148, 2024). "We designed and developed a MerTK specific antisense oligonucleotide (ASO) and characterized its effects on eliciting an anti-tumor immune response in mice." (PMID 38443968, 2024). "The MDK/LRP1, MDK/ALK, GAS6/MERTK, and GAS6/AXL were identified as potential ligand-receptor pairs involved in the interactions between fibroblasts/endothelial cells and tumor cells." (PMID 37733241, 2023). "Further, our results identified potential ligand-receptor pairs (MDK/LRP1, MDK/ALK, GAS6/MERTK, and GAS6/AXL) for cell communication between these two types of cells and tumor cells." (PMID 37733241, 2023). "Blockade of MerTK by an antibody promotes the accumulation of apoptotic cells within tumors to induce macrophage STING activation and anti-tumor immunity." (PMID 37422464, 2023). "We next evaluated roles for MERTK, EGFR, and AXL in NSCLC tumor cell expansion, migration, and colony formation using siRNA-mediated knockdown." (PMID 35708914, 2022). "MerTK activity has also been shown to play a role in endothelial cell recruitment to the TME and to inhibit angiogenesis, thus hindering tumour development and growth." (PMID 36555321, 2022). "MERTK and AXL operate in innate immune cells to suppress inflammatory responses and promote an immunosuppressive tumour microenvironment, while AXL expression correlates with epithelial-to-mesenchymal transition, metastasis, and motility in tumours." (PMID 35626092, 2022). "A study on murine MC38 colon cancer found that MerTK blockade induced an accumulation of apoptotic cells in cancers, the production of local type I IFN, and an increase in tumor immunogenicity, thus indicating the potential of cancer immunotherapy." (PMID 36497444, 2022). "TAM receptors promote tissue-specific macrophage polarisation into a pro-tumour M2-like phenotype as AXL and TYRO3 regulate phagocytosis in dendritic cells, whereas MERTK do so in the thymus and retina." (PMID 35626092, 2022). "In the hereby presented proof-of-concept study, targeted phagocytosis for cancer immunotherapy was substituted by targeting MerTK on macrophages and the epidermal growth factor receptor (EGFR) that is overexpressed on a plethora of tumour types." (PMID 36555321, 2022). "Both MERTK and AXL enhance the immunosuppressive nature of the tumour niche, as they are expressed on macrophages, NK cells, and dendritic cells." (PMID 35626092, 2022). "In tumor-bearing mice, the expressions of TYRO3, AXL, and MERTK, and their ligands increased >20 folds in M-MDSCs and >15 folds in PMN-MDSCs." (PMID 36131911, 2022).